TGFBI (transforming growth factor beta induced)
Diseases named in the same sentence as TGFBI in open-access papers (continued):
Sharing a sentence is not in itself a finding about the gene and the disease.
Alzheimer disease (6 papers, 2013 to 2024). A progressive, neurodegenerative disease characterized by loss of function and death of nerve cells in several areas of the brain leading to loss of cognitive function such as memory and language. "HtrA1 has previously been shown to colocalize with the corneal amyloid associated with the V624M mutation in TGFBI and with β-amyloid plaques in Alzheimer disease." (PMID 23592924, 2013). "Supermeres are highly enriched with cargo involved in multiple cancers (glycolytic enzymes, TGFBI, miR-1246, MET, GPC1 and AGO2), Alzheimer’s disease (APP) and cardiovascular disease (ACE2, ACE and PCSK9)." (PMID 34887515, 2021). "In the study of Alzheimer’s disease, it was discovered that although APP itself is a target of miRNA regulation, amyloid β protein can downregulate miRNAs, including miR-181c and miR-9, both of which inhibit the expression of TGFBI." (PMID 38725646, 2024).
atherosclerosis (6 papers, 2013 to 2025). A disease characterized by the build-up of fatty material and calcium deposition in the arterial wall resulting in partial or complete occlusion of the arterial lumen. "Several papers have described mutations of the TGFBI gene, which may be related to RA, DM, atherosclerosis and other systemic diseases." (PMID 23837658, 2013). "In conclusion, a Venn diagram illustrated TGFBI, GMFG, and CTSC as key genes associated with both atherosclerosis and disulfidptosis." (PMID 40299531, 2025). "Machine learning-based techniques, including LASSO, Boruta, Support Vector Machine, and Random Forest, were employed to specifically identify CTSC, TGFBI, and GMFG as potential diagnostic biomarkers associated with SMC activity in atherosclerosis." (PMID 40299531, 2025). "Although direct evidence linking TGFBI to atherosclerosis is limited, its interaction with the extracellular matrix implies a potential role in the progression of the disease." (PMID 40299531, 2025). "Through single-cell RNA sequencing and machine learning, we pinpointed CTSC, TGFBI, and GMFG as key biomarkers for atherosclerosis risk stratification." (PMID 40299531, 2025). "Recently, we were able to show that genetic single Stabilin deficiency and anti-Stabilin antibody therapy in different atherosclerosis-prone mouse models ameliorate atherosclerosis, likely through altered immune cell activation mediated by a plasma proteome switch including TGFBi and POSTN." (PMID 37446152, 2023). "In the smooth muscle cell (SMC)-focused in vitro model of atherosclerosis, RT-qPCR analysis demonstrated that the expression levels of CTSC, TGFBI, and GMFG were significantly elevated compared to those in the control group." (PMID 40299531, 2025).
bladder cancer (6 papers, 2019 to 2026). "We also identified associations between TGFBI expression and prognosis of lung squamous cell, gastric, colorectal, and bladder cancer, which concurs with previous studies." (PMID 34671645, 2021). "Our results are further supported by a study from Shang and colleagues, who demonstrated in RT112 and 253J bladder cancer cell lines, that siRNA-mediated low TGFBI expression significantly decreased proliferation, adhesion, migration and invasion." (PMID 31514337, 2019). "To understand the signaling cascade leading to the expression and release of TGFBI in bladder cancer cells, we investigated the effects of the TGF-β-receptor type I inhibitor SB-431542 on 5637 cells." (PMID 31514337, 2019). "In contrast, overexpression of TGFBI in these bladder cancer cells significantly enhanced all those cellular functions." (PMID 31514337, 2019). "The elevated urinary TGFBI concentration in patients with high-grade UC suggests biological functions of this protein in bladder cancer." (PMID 31514337, 2019). "TGFBI is secreted by bladder cancer cells to induce proliferation, migration, and invasion, as well as EMT in an autocrine manner." (PMID 31842336, 2019). "Herein, we discovered that the enhanced hypoxia-induced transforming growth factor beta induced protein (TGFBI) in bladder cancer (BLCA) promotes the establishment of a stemness loop in the tumor microenvironment, facilitating the maintenance of CSC stemness and malignant proliferation." (PMID 41684953, 2026). "Hence, the expression and secretion of TGFBI by bladder cancer cells is critical for their migratory activity." (PMID 31514337, 2019). "Additionally, we performed knockdown experiments with TGFBI siRNA in bladder cancer cells and investigated the effects on proliferation and migration by wound closure assays and BrdU cell cycle analysis." (PMID 31514337, 2019). "Moreover, TGFBI overexpression stimulates the growth of bladder cancer xenografts in mice." (PMID 31842336, 2019). "Thus, TGFBI secretion supports the growth of bladder cancer cells by increasing cell proliferation." (PMID 31514337, 2019). "Therefore, in addition, we investigated the function of TGFBI in vitro in the human-derived urinary bladder cell line 5673 (grade II;) by blocking its release and examining whether in vitro siRNA-mediated TGFBI suppression in these bladder cancer cells affects proliferation and migration." (PMID 31514337, 2019).
cholangiocarcinoma (6 papers, 2015 to 2024). A carcinoma that arises from the intrahepatic biliary tree (intrahepatic cholangiocarcinoma) or from the junction, or adjacent to the junction, of the right and left hepatic ducts (hilar cholangiocarcinoma). "Among the downstream genes of TGF-β, TGFBI was focused as one of the candidates of EMT regulator because TGFBI expression was found to be upregulated in cholangiocarcinoma (CC) cells exhibiting mesenchymal sarcomatous changes relative to epithelial CC cells." (PMID 28106769, 2017). "TGFBI is overexpressed in non-Opisthorchis viverrini-related intrahepatic cholangiocarcinoma (CC); this is associated with sarcomatous changes such as EMT induction, which leads to aggressive intrahepatic spreading and metastasis in CC." (PMID 28106769, 2017). "Overexpression of TGFBI alone promoted cholangiocarcinoma cell migration and EMT changes, but not spheroid formation, suggesting that TGFBI partially contributes to LIN28B-mediated aggressive cell behaviour." (PMID 34548635, 2022). "In addition, LIN28B promotes migration and proliferation in cholangiocarcinoma through TGF-β-induced protein (TGFBI), although a mechanistic relationship between LIN28B and TGFBI mRNA 3′ UTR has not yet been verified." (PMID 37370851, 2023).
Cirrhosis (6 papers, 2019 to 2022). A chronic disorder of the liver in which liver tissue becomes scarred and is partially replaced by regenerative nodules and fibrotic tissue resulting in loss of liver function. "TGFBI (Transforming growth factor beta induced) was recently confirmed to be strongly associated with NAFLD and cirrhosis in humans." (PMID 33467660, 2021). "Furthermore, a global correlation map of clinical and proteomic data strongly associated DPP4, ANPEP, TGFBI, PIGR, and APOE with NAFLD and cirrhosis." (PMID 30824564, 2019). "Seven DEGs (TYMP, TYROBP, CD14, TGFBI, LILRA2, GNLY, and GZMB) were common to HCC, cirrhosis, and CHB when compared to healthy controls." (PMID 35265561, 2022). "We found them to be upregulated in cirrhosis represented by the upregulation of PGDFRB, TGFB1 (TGF‐β1), TGFB1I1 (TGF‐β1 induced transcript 1 protein), TGFBI (TGF‐β induced protein ig‐h3), LTBP1, LTBP2, LTBP4, and ENG (transmembrane accessory receptor for TGF‐beta signaling)." (PMID 35579278, 2022).
diabetes (6 papers, 2012 to 2023). "When we analyzed TGFβ-associated genes, we were astonished that several triggers like TGFβ2 and TGFBI were significantly activated by diabetes, while several suppressors like TGIF1 and TGIF2 were significantly deactivated by diabetes." (PMID 35935990, 2022).
cervical cancer (5 papers, 2017 to 2024). A primary or metastatic malignant neoplasm involving the cervix. "Future studies are warranted to confirm these findings, because in another study TGFBI expression was also shown to be increased in cervical cancer tissue." (PMID 39587670, 2024). "Overexpression of TGFBI is related to poor prognosis in cervical cancer." (PMID 34950205, 2021). "Among them, AK4, P4HA1 and TGFBI were first confirmed as oncogene in cervical cancer." (PMID 34217310, 2021). "The functional study shown that expression of AK4, HK2, P4HA1, TGFBI and VEGFA can regulate the proliferation, migration, and invasion ability of cervical cancer cells in vitro." (PMID 34217310, 2021). "The results obtained with RT-PCR and immunohistochemistry assays both showed that AK4, HK2, P4HA1, TGFBI and VEGFA were all highly expressed in these cervical cancer tissue samples." (PMID 34217310, 2021). "The functional study shown that expression of AK4, HK2, P4HA1, TGFBI and VEGFA can regulate the proliferation, migration, and invasion ability of cervical cancer cells." (PMID 34217310, 2021). "The colony formation and transwell assays results showed that reduced AK4, HK2, P4HA1, TGFBI and VEGFA expression, which significantly inhibited proliferation, migration and invasion ability of cervical cancer cells." (PMID 34217310, 2021). "Moreover, the result of RT-PCR and immunohistochemistry demonstrated that AK4, HK2, P4HA1, TGFBI and VEGFA were all highly expressed in these cervical cancer tissue samples." (PMID 34217310, 2021). "Furthermore, to verify the accuracy of the 5-gene signature, we examined the expression of the signature genes (AK4, HK2, P4HA1, TGFBI and VEGFA) in clinical samples from 10 cervical cancer patients by qPCR and IHC analysis." (PMID 34217310, 2021). "Moreover, the results of qPCR and immunohistochemistry staining assay revealed that the expression of AK4, HK2, P4HA1, TGFBI and VEGFA is high in cervical cancer." (PMID 34217310, 2021). "Regarding TGFBI, we found the highest median concentration in the urine of UCa patients independent from UCa history, and an enhanced median concentration in the group of women with cervical cancer when compared to non-cancer patients." (PMID 39587670, 2024).
clear cell renal cell carcinoma (5 papers, 2020 to 2024). "A study has confirmed that TGFBI serving as a ubiquitination substrate is reduced in clear cell renal cell carcinoma (ccRCC)." (PMID 35967373, 2022). "Cancer-specific survival was significantly better for patients with no cytoplasmic TGFBI expression in clear cell renal cell carcinoma as well." (PMID 38395907, 2024).
COVID-19 (5 papers, 2021 to 2025). A disease caused by infection with severe acute respiratory syndrome coronavirus 2. "Macrophages from patients with IPF and COVID-19 were both found to express fibrosis-associated genes including Secreted Phosphoprotein 1 (SPP1), transforming growth factor beta 1 (TGFB1), transforming growth factor beta-induced (TGFBI), legumain (LGMN), and C-C Motif Chemokine Ligand 18 (CCL18)." (PMID 37759460, 2023). "Coincidently, TGFBI K676 is acetylated in the blood of COVID-19 patients with severe pneumonia." (PMID 35159281, 2022). "Further analysis of gene importance across the four models revealed that the top four hub genes in COVID-19 were CR1, TNFRSF10C, TAP2, and TGFBI, while the top four hub genes in SS-KCS were CR1, IL13, TAP2, and IL1R2." (PMID 40149556, 2025).
Nephropathy (5 papers, 2020 to 2023). A nonspecific term referring to disease or damage of the kidneys. "It was demonstrated that TGFBI was involved in the fibrotic processes of chronic cyclosporine-induced nephropathy by affecting the synthesis and degradation of the extracellular matrix." (PMID 35663304, 2022). "TGFBI, a protein that is produced in response to transforming growth factor beta (TGF-β), has been shown to have significant implications in various kidney diseases." (PMID 38130724, 2023).
neuroblastoma (5 papers, 2007 to 2025). Neuroblastoma (NB) is the most common solid, extracranial childhood tumor. "MYCN pro-to-oncogene (MYCN) suppresses TFPI2 and promotes tumor invasiveness, while TGFBI counteracts this by restoring TFPI2 expression in neuroblastoma." (PMID 40361374, 2025). "It has been described that TGFBI could inhibit cell adhesion to various ECM proteins inhibiting cell proliferation and invasion in neuroblastoma." (PMID 31277676, 2019). "We present eight genes (KRT19, PRKCDBP, SCNN1A, POU2F2, TGFBI, COL1A2, DHRS3 and DUSP23) that are methylated in neuroblastoma, most of them not previously reported as such, some of which also distinguish between biological subsets of neuroblastoma tumors." (PMID 21314941, 2011).
renal cell carcinoma (5 papers, 2012 to 2024). "In summary, our study demonstrated experimentally for the first time that TGFBI is highly expressed in renal cell carcinoma, as well as facilitates renal cancer cells migration and invasion." (PMID 39068456, 2024). "The findings indicate that TGFBI exhibits significantly elevated expression levels in both renal cell carcinoma (RCC) tissues and cells." (PMID 39068456, 2024). "However, there are still few studies on the role of TGFBI in renal cell carcinoma, and the biological process of its expression and participation in renal cell carcinoma is still unclear, which is worthy of further exploration." (PMID 39068456, 2024). "Moreover, we further proved that TGFBI participates in the EMT process of renal cell carcinoma and affects the occurrence and development of renal cancer through the PI3K/AKT/mTOR/HIF-1α signaling pathway." (PMID 39068456, 2024).
Sepsis (5 papers, 2020 to 2026). Sepsis is defined as life-threatening organ dysfunction caused by a dysregulated host response to infection. "Clustering based on the expressions of TGFBI and MAD1L1 was significantly associated with sepsis characteristics and prognoses (all P < 0.05)." (PMID 38412321, 2024). "Subsequently, we conducted GSEA after dividing the monocytes or B cells from sepsis samples into low- and high-expression subgroups based on the median expression level of TGFBI or MAD1L1." (PMID 38412321, 2024). "In our study, we reported for the first time that TGFBI and MAD1L1 could act as diagnostic and prognostic biomarkers in sepsis, and their association with cellular senescence of monocytes and B cells." (PMID 38412321, 2024). "Our findings show that targeting TGFBI and MAD1L1, given their close association with monocytes and B cells, could be promising therapeutic options for sepsis." (PMID 38412321, 2024). "The present study established a gene signature related to cellular senescence that included TGFBI and MAD1L1 to evaluate the prognosis and the occurrence in sepsis." (PMID 38412321, 2024). "We analyzed the expression levels of TGFBI and MAD1L1 in both the control and sepsis samples." (PMID 38412321, 2024).
Blindness (4 papers, 2017 to 2023). Blindness is the condition of lacking visual perception defined as a profound reduction in visual perception. "Corneal dystrophiesare TGFBI (transforming growth factor beta-induced) protein-associateddisorders caused primarily by TGFBI protein aggregation in the cornea,which may lead to blindness in severe cases." (PMID 38144115, 2023).
brain tumor (4 papers, 2009 to 2025). "TGFBI had been reported to exhibit higher serum levels in brain tumor patients compared to non-tumor patients." (PMID 35673564, 2022).
breast tumor (4 papers, 2014 to 2021). "Indeed, our analyses reveal that there is a positive association between TGFBI expression and M2 macrophage content in human breast tumours." (PMID 33080107, 2020). "In silico analyses using the METABRIC cohort confirmed that the expression of TGFBI in human breast tumours positively correlates with the expression of many hypoxia‐related genes." (PMID 33080107, 2020). "Downregulation of TGFBI is reported in tumor cell lines and in patients with lung and breast tumors." (PMID 25369402, 2014). "TGFBI expression also reduced the metastatic potential of lung and breast tumor cells." (PMID 33912443, 2021). "Moreover, the levels of expression of TGFBI in human breast tumours significantly correlate with their molecular subtype." (PMID 33080107, 2020). "TGFBI-expressing cells were found to inhibit tumor cell invasion through the downregulation of MMP-2 and MMP-9 in lung and breast tumor cells." (PMID 30453668, 2018).
corneal opacities (4 papers, 2013 to 2021). "We used a stereomicroscope to analyse the effects of the TGFBI-R124C mutation on the development of corneal opacity in mice." (PMID 32029872, 2020). "Human patients bearing TGFBI-R124H homozygous mutations present with more severe corneal opacity than patients harbouring heterozygous mutations." (PMID 32029872, 2020). "The corneal opacities are result of a specific mutation (R124H) in transforming growth factor beta-induced gene (TGFBI, OMIM 601692, formerly called BIGH3)." (PMID 23837658, 2013). "In TGFBI-R124C homozygous mice, corneal opacity was observed in 51 of 71 mice (71.8%) at 20 weeks of age and in 57 mice (80.3%) at 40 weeks of age." (PMID 32029872, 2020). "Among the TGFBI-R124C mice with unilateral corneal opacity, some mice developed bilateral corneal opacity." (PMID 32029872, 2020). "In summary, total number of the eye showed corneal opacity at 40 weeks of age are 105 (73.9%) and 2 (9.1%) in the TGFBI-R124C homozygous and heterozygous mice, respectively." (PMID 32029872, 2020). "Over 71% of the diseased TGFBI-R124C homozygous mice showed bilateral corneal opacity at 12 weeks of age, and the percentage gradually increased to 91% at 40 weeks of age, whereas 5 mice developed unilateral corneal opacity." (PMID 32029872, 2020). "The correction of TGFBI mutations in the local cornea may be a radical treatment for GCD patients, minimizing progression and the recurrence of corneal opacities." (PMID 29196743, 2017).
diabetic nephropathy (4 papers, 2016 to 2023). "Han used machine learning to obtain two diagnostic markers of protein kinase cAMP-dependent type II regulatory subunit beta and transforming growth factor beta 1 (PRKAR2B and TGFBI, respectively) in glomerular injury in diabetic nephropathy." (PMID 36960398, 2023). "The miR-1237-3p/SH2B3, miR-1238-5p/ZNF652 and miR-766-3p/TGFBI axes may be involved in diabetic nephropathy." (PMID 32778679, 2020). "Therefore, the miR-1237-3p/SH2B3, miR-1238-5p/ZNF652 and miR-766-3p/TGFBI axes may be involved in diabetic nephropathy." (PMID 32778679, 2020). "The miRNA-mRNA network suggested that the miR-766-3p/TGFBI, miR-1238-5p/ZNF652 and miR-1237-3p/SH2B3 axes may be involved in diabetic nephropathy and that most target genes have differences in DNA methylation levels between the DN group and the control group." (PMID 32778679, 2020).